GRID2IP (Grid2 interacting protein)
Description:
Postsynaptic scaffolding protein at the parallel fiber-Purkinje cell synapse, where it may serve to link GRID2 with actin cytoskeleton and various signaling molecules.
Synonyms: DELPHILIN
Tractability: Antibody: UniProt places it where antibodies can reach, with medium confidence; its Gene Ontology location is reachable by antibodies, with medium confidence; the Human Protein Atlas places it where antibodies can reach.
Gene: Protein-coding gene on chromosome 7 (6,496,778 to 6,551,461, reverse strand). Ensembl gene ENSG00000215045.
Subcellular location: Postsynaptic cell membrane
Subcellular location (Human Protein Atlas): Plasma membrane
Gene Ontology:
Molecular function: protein binding
Biological process: regulation of postsynaptic cytosolic calcium ion concentration; regulation of postsynaptic membrane neurotransmitter receptor levels
Cellular component: cerebellar granule cell to Purkinje cell synapse; glutamatergic synapse; parallel fiber to Purkinje cell synapse; postsynaptic density, intracellular component; postsynaptic membrane; synapse
Genetic constraint (gnomAD): Loss-of-function variants: 70 observed, 95.33 expected, observed/expected ratio (o/e) 0.73, 90% interval 0.61 to 0.9. The synonymous counts are far from expectation, so gnomAD's model fits this gene poorly and the ratio says little. Missense variants: 1,583 observed, 1,447.1 expected, observed/expected ratio (o/e) 1.09, 90% interval 1.05 to 1.14. Synonymous variants: 751 observed, 618.52 expected, observed/expected ratio (o/e) 1.21, 90% interval 1.14 to 1.29.
Homologues: Orthologues: macaque GRID2IP (98% identical), pig GRID2IP (94% identical), guinea pig GRID2IP (93% identical), rat Grid2ip (91% identical), mouse Grid2ip (91% identical), chimpanzee GRID2IP (84% identical), dog GRID2IP (80% identical), rabbit GRID2IP (78% identical), zebrafish grid2ipa (59% identical), zebrafish grid2ipb (56% identical), tropical clawed frog grid2ip (46% identical), Caenorhabditis elegans daam-1 (12% identical), and 1 more. Paralogues in human: FMN2 (17% identical), DAAM1 (16% identical), INF2 (16% identical), DAAM2 (15% identical), DIAPH1 (15% identical), FHOD3 (14% identical), DIAPH2 (14% identical), FMNL1 (14% identical), DIAPH3 (14% identical), FMNL3 (13% identical), FMNL2 (13% identical), FHOD1 (12% identical), and 6 more.
Diseases named in the same sentence as GRID2IP in open-access papers:
GRID2IP is named in the same sentence as 16 diseases in open-access papers, as found by Europe PMC text mining. Sharing a sentence is not in itself a finding about the gene and the disease. The quoted sentences say what the papers report.
cholangiocarcinoma (2 papers, 2020 to 2023). A carcinoma that arises from the intrahepatic biliary tree (intrahepatic cholangiocarcinoma) or from the junction, or adjacent to the junction, of the right and left hepatic ducts (hilar cholangiocarcinoma). "An analysis of the TCGA database has also implicated GRID2IP as a novel prognostic marker in patients with cholangiocarcinoma." (PMID 32206039, 2020). "The results show that GRID2IP is found in bladder carcinoma(BLCA), cholangiocarcinoma (CHOL), colon adenocarcinoma(COAD), lung adenocarcinoma(LUAD) was highly expressed and low expressed in KICH, KIRC and HNSC." (PMID 37964339, 2023).
asthma (1 paper, 2022). "Both ZPBP2 and GRID2IP are part of loci that have been previously associated with autoimmune disease, including asthma and inflammatory bowel diseases (IBDs)." (PMID 35814780, 2022).
Autoimmunity (1 paper, 2022). The occurrence of an immune reaction against the organism's own cells or tissues. "Together, this suggests that GRID2IP may have an unrecognized role in autoimmunity." (PMID 35814780, 2022).
cardiac hypertrophy (1 paper, 2017). "In addition, two SNVs in genes RGD1565131 and Grid2ip were found to be associated with cardiac hypertrophy." (PMID 28130354, 2017).
colorectal cancer (1 paper, 2023). A primary or metastatic malignant neoplasm that affects the colon or rectum. "It’s suggesting that the GRID2IP’s expression was higher in the colorectal cancer line cells." (PMID 37964339, 2023).
hepatocellular carcinoma (1 paper, 2024). A malignant tumor that arises from hepatocytes. "The methylation of specific genes, including VASH2, CHFR, GRID2IP, CCNJ, SEPT9, and F12, is considered a biomarker for the onset of hepatocellular carcinoma (HCC)." (PMID 38473997, 2024).
vitiligo (1 paper, 2022). Generalized well circumscribed patches of leukoderma that are generally distributed over symmetric body locations and is due to autoimmune destruction of melanocytes. "GRID2IP expression is strongly upregulated in peripheral blood mononuclear cells of patients with vitiligo." (PMID 35814780, 2022).
cancer (2 papers, 2020 to 2023). A tumor composed of atypical neoplastic, often pleomorphic cells that invade other tissues. "Aim to investigate the general expression of GRID2IP in various cancers, we first analyzed pan-cancer, compared the expression of GRID2IP in GTEx combined with TCGA samples, and performed Wilcoxon rank sum test analysis on matched samples in TCGA." (PMID 37964339, 2023). "Based on the TCGA database, we found that GRID2IP in many kinds of cancer patients were significantly different from that in normal controls." (PMID 37964339, 2023). "Although the three genes (GRID2IP, TMEM117, HLA-DP) are involved in the progression of cancers, their role in GC is unclear." (PMID 32206039, 2020). "To understand the relationship between GRID2IP and MSI status in CRC patients, we evaluated the correlation between MSI and TMB scores and GRID2IP in pan-cancer, and further visualized the correlation between MSI and TMB and GRID2IP in CRC patients with scatter plots." (PMID 37964339, 2023).
tumor (2 papers, 2023). "In our study, we used transcriptome data retrieved from the TCGA database to identify the effect of GRID2IP on prognosis and tumor-associated immune cells in CRC." (PMID 37964339, 2023). "The rise of GRID2IP inhibits the invasion of tumor-associated immune cells resulting in a lower immune score." (PMID 37964339, 2023). "GRID2IP plays a role in the modulation of tumor-associated immune cells." (PMID 37964339, 2023). "Our results suggest that rising GRID2IP promotes tumor-associated immune cell infiltration and suggests adverse outcomes in CRC patients, which may be a useful biomarker for determining the prognosis of CRC and a potential target molecule for CRC therapy." (PMID 37964339, 2023). "We identified that GRID2IP is substantially expressed in tumor tissues and that its expression indicates a poor prognosis for CRC in our investigation." (PMID 37964339, 2023). "The ROC curve confirmed that using the expression level of GRID2IP to distinguish between normal tissue and tumor tissue has a certain specificity (AUC = 0.728)." (PMID 37964339, 2023). "The results showed that up-regulation of GRID2IP was related to worse clinical features, which includes T-stage, N-stage, M-stage, pathology stage, BMI, residual tumor, lymphatic invasion, CEA level, tumor status." (PMID 37964339, 2023). "In the paired sample, we discovered that GRID2IP expression was substantially higher in tumor tissues than in normal tissues." (PMID 37964339, 2023). "Grouped based on clinic pathology and independent prognostic factors, we observed T-stage (T3&T4), N-stage (N1&N2), pathology stage (T3&T4), residual tumor(R1&R2), lymphatic invasion, BMI (< 25) subgroups with high expression of GRID2IP had worse prognosis." (PMID 37964339, 2023). "Moreover, the involvement of high-expression GRID2IP in tumor immunity was mainly related to T cells and innate immune cells, including T cells, CD8 + T cells, Macrophages, Neutrophils, DC cell, T helper cells, Th1 cells, Th2 cells." (PMID 37964339, 2023). "Moreover, the AUC diagnosed by the clinical ROC curve was 0.728, indicating that GRID2IP is a convincing biomarker for judging tumor tissue." (PMID 37964339, 2023). "We analyzed the differences in GRID2IP expression between different subgroups by Cox regression analysis, and found that GRID2IP was significantly correlated with some clinical features, including N-stage, M-stage, pathology stage, residual tumor, lymphatic invasion, CEA level, BMI." (PMID 37964339, 2023). "Moreover, ROC curve was applied to identify the differential performance of GRID2IP, and the result showed that the area under the curve(AUC) value was 0.728, indicating that GRID2IP gene has a potential role in differentiating normal tissues from tumor tissues." (PMID 37964339, 2023). "The effect of GRID2IP on the prognosis of CRC and its effect on tumor microenvironment remains unclear." (PMID 37964339, 2023).
infection (1 paper, 2016). The state of being infected such as from the introduction of a foreign agent such as serum, vaccine, antigenic substance or organism. "To confirm our results, we also examined infection by microscopy after depletion of FHOD1, FMNL3, GRID2IP or INF2; all four decreased bacterial uptake, though depletion of FMNL3 had the weakest effect." (PMID 27152864, 2016).
GRID2IP also shares sentences with these, for which no sentence is quoted: autoimmune disease (1 paper); bladder carcinoma (1); Cirrhosis (1); colon adenocarcinoma (1); inflammatory bowel disease (1); lung adenocarcinoma (1).